MIR3064 (microRNA 3064)
Synonyms: hsa-mir-3064
Gene: MicroRNA gene on chromosome 17 (64,500,774 to 64,500,839, reverse strand). Ensembl gene ENSG00000284564.
Homologues: Orthologues: chimpanzee MIR3064 (100% identical).